TNNT1 (troponin T1, slow skeletal type)
Description:
Troponin T is the tropomyosin-binding subunit of troponin, the thin filament regulatory complex which confers calcium-sensitivity to striated muscle actomyosin ATPase activity.
Synonyms: TnTs; sTnT; TNT; ANM; FLJ98147; MGC104241; NEM5
Tractability: No criterion of Open Targets' tractability assessment is met for any kind of drug.
Gene: Protein-coding gene on chromosome 19 (55,132,698 to 55,149,351, reverse strand). Ensembl gene ENSG00000105048.
Subcellular location (Human Protein Atlas): Cytosol; Golgi apparatus; Nucleoplasm
Pathways (Reactome):
Muscle contraction: Striated Muscle Contraction
Gene Ontology:
Molecular function: protein binding; tropomyosin binding; troponin T binding
Biological process: negative regulation of muscle contraction; skeletal muscle contraction; sarcomere organization; slow-twitch skeletal muscle fiber contraction; regulation of muscle contraction
Cellular component: troponin complex; cytosol
Genetic constraint (gnomAD): Loss-of-function variants: 51 observed, 45.5 expected, observed/expected ratio (o/e) 1.12, 90% interval 0.89 to 1.41. The upper end of that interval is the gene's LOEUF score, 1.41, which puts it in group 5 of 6, group 1 being the genes least tolerant of losing a copy. Missense variants: 345 observed, 370.85 expected, observed/expected ratio (o/e) 0.93, 90% interval 0.85 to 1.02. Synonymous variants: 142 observed, 136.5 expected, observed/expected ratio (o/e) 1.04, 90% interval 0.91 to 1.2.
Gene-disease validity (ClinGen):
ClinGen rates the evidence that TNNT1 causes each of these diseases.
nemaline myopathy 5 (autosomal recessive): Definitive. Amish nemaline myopathy is a type of nemaline myopathy (NM) only observed in several families of the Amish community.
nemaline myopathy (autosomal dominant): Limited. Nemaline myopathy (NM) encompasses a large spectrum of myopathies characterized by hypotonia, weakness and depressed or absent deep tendon reflexes, with pathologic evidence of nemaline bodies (rods) on muscle biopsy.
Homologues: Orthologues: chimpanzee TNNT1 (99% identical), dog PPP6R1 (91% identical), mouse Tnnt1 (90% identical), rat Tnnt1 (90% identical), guinea pig TNNT1 (87% identical), macaque TNNT1 (82% identical), tropical clawed frog tnnt1 (79% identical), zebrafish tnnt1 (67% identical), pig TNNT1 (60% identical), Caenorhabditis elegans tnt-3 (38% identical), Drosophila melanogaster up (35% identical). Paralogues in human: TNNT2 (60% identical), TNNT3 (58% identical).
Diseases named in the same sentence as TNNT1 in open-access papers:
TNNT1 is named in the same sentence as 57 diseases in open-access papers, as found by Europe PMC text mining. Sharing a sentence is not in itself a finding about the gene and the disease. The quoted sentences say what the papers report.
nemaline myopathy (14 papers, 2013 to 2025). "In the present study, we aimed to determine how TNNT1 variants linked to nemaline myopathy induce muscle cell dysfunction." (PMID 40320982, 2025). "To date, only a limited number of patients with nemaline myopathy caused by TNNT1 variants have been reported in the literature." (PMID 34440373, 2021). "In comparison to human variants, the only confirmed human TNNT1 nemaline myopathy cases that show production of intact TNNT1 protein are autosomal dominant cases caused by a missense variant within one of the two highly conserved tropomyosin binding sites." (PMID 32819427, 2020). "TNNT1 was an attractive candidate for further validation due to association with nemaline myopathy in humans and its type I myofibre specificity." (PMID 32819427, 2020). "This suggests that OCPMD is a nemaline myopathy with dystrophic features, since variants in TNNT1 have been previously associated with recessive and dominant nemaline myopathy across multiple human populations." (PMID 32819427, 2020). "TNNT1 appears to be emerging as a causative gene for both recessive and dominant nemaline myopathy outside the Old Order Amish population." (PMID 29178646, 2017). "This study describes the first TNNT1 mutation that transmits in an autosomal dominant fashion to cause nemaline myopathy." (PMID 29178646, 2017). "Another case report of a Dutch patient of inherited nemaline myopathy described two new TNNT1 NM mutations." (PMID 27790152, 2016). "Multiple mutations in TNNT1 gene, located at 19q13.42 in the human genome, have been identified to cause autosomal recessively inherited nemaline myopathies." (PMID 27790152, 2016). "In 2000, a pathogenic TNNT1 founder variant characterized by a stop codon in exon 11 was identified in the North American Amish community, associated with a form of congenital myopathy named nemaline myopathy (NM) type 5 (NEM5, MIM 605355) on muscle biopsy." (PMID 40320982, 2025). "Mutations in TNNT1 have been reported to result in nemaline myopathy." (PMID 38173464, 2023). "Nonsense or missense TNNT1 variants have been associated with skeletal muscle weakness and contractures and a histopathological appearance of nemaline myopathy (NM) on muscle biopsy." (PMID 40320982, 2025). "By applying SMPFO to two forms of human nemaline myopathy (ACTA1 and TNNT1 mutations), we reveal significant reduction in the divergence of myofibre subtypes across both biophysical and proteomic behaviour." (PMID 40320980, 2025). "Onset in childhood or at juvenile age often implies a mild course, while recessively inherited TNNT1 (Amish) nemaline myopathy follows a relentlessly progressive course, with thoracic immobility, restrictive lung disease and often death in childhood." (PMID 31228046, 2019). "In Tnnt1 mice, depicting the “Amish” form of nemaline myopathy, there was severe weakness of the diaphragm, as in human patients, and an increase in fast 2B fibre types, but this myosin isoform is not expressed in human limb muscle." (PMID 31228046, 2019). "Rather, the majority of human cases of TNNT1 nemaline myopathy are caused by autosomal recessive nonsense mutations that prevent incorporation of TNNT1 into the myofilament, leading to rapid protein degradation." (PMID 32819427, 2020). "As results, several recent reports have identified four more TNNT1 mutations in non-Amish ethnic groups, which cause nemaline myopathies clinically similar to ANM." (PMID 27790152, 2016). "TNNC2 has been implicated in a novel congenital myopathy, TNNI2 and TNNT3 in distal arthrogryposis (DA), and TNNT1 and TNNT3 in nemaline myopathy (NEM)." (PMID 34502093, 2021). "However, as the histopathology also shows features of other myopathies (e.g. protein aggregation, dystrophic changes), we believe it is most appropriate to class OCPMD as a model of ‘TNNT1 congenital myopathy’ rather than nemaline myopathy, specifically." (PMID 32819427, 2020).
nemaline myopathy (continued). "This difference may also explain the lack of dystrophic features in cases of human TNNT1 nemaline myopathy compared to the OCPMD model." (PMID 32819427, 2020). "A prime example is nemaline myopathy (NM), the most common non-dystrophic congenital skeletal muscle myopathy that is caused by mutations in six genes that all encode thin filament proteins (TMP2, TMP3, NEB, ACTA1, TNNT1, CFL2)." (PMID 23437068, 2013).
colorectal cancer (7 papers, 2022 to 2025). A primary or metastatic malignant neoplasm that affects the colon or rectum. "TNNT1 was shown to be associated with various cancers, such as colorectal cancer." (PMID 36544490, 2022). "Studies by Yu Chen and colleagues have empirically established TNNT1’s oncogenic role in colorectal cancer progression." (PMID 41127012, 2025). "During the metastasis process, we observed significant increases in the expression of the TPM2, RPS17, and TNNT1 genes in colorectal cancer epithelial cells, while SPINK4 expression was notably reduced." (PMID 41127012, 2025). "The expression levels of TPM2, RPS17, and TNNT1 progressively increased during the progression and metastasis of colorectal cancer (CRC); in contrast, SPINK4 expression initially rose before sharply declining." (PMID 41127012, 2025). "Recently, many articles have pointed out that Tnnt1 expression was closely correlated with the development of colorectal cancer and breast cancer." (PMID 37477865, 2024). "TNNT1 is regulated by miR-873 to promote colorectal cancer progression." (PMID 40709170, 2025). "In addition, several studies have disclosed that Tnnt1 expression was significantly increased in colorectal cancer." (PMID 37477865, 2024). "TNNT1 is regulated by miR-873 and confirmed as an oncogene of colorectal cancer (CRC)." (PMID 38095640, 2023). "In addition, another study reported TNNT1 overexpression in colorectal cancer cells, where it enhances their proliferation, migration, and invasion capacities." (PMID 35712127, 2022). "During liver metastasis in colorectal cancer, the expression levels of TPM2, RPS17, and TNNT1 were significantly elevated, SPINK4 expression was reduced in the epithelial cells." (PMID 41127012, 2025). "The expression levels of TPM2, RPS17, and TNNT1 were significantly elevated, while SPINK4 expression was reduced in the epithelial cells of colorectal cancer with liver metastasis." (PMID 41127012, 2025).
breast carcinoma (6 papers, 2018 to 2025). "Studies demonstrated that TNNT1 involved in breast cancer cell proliferation and highly expressed in leiomyosarcoma metastases, while its role in PDAC remained mystic." (PMID 30598639, 2018). "TNNT1 expression was upregulated in some of the invasive forms of colorectal and breast cancer." (PMID 40433700, 2025). "TNNT1 promotes the proliferation of breast cancer cells by promoting the G1/S transition." (PMID 34950653, 2021). "In addition, TNNT1 may also promote the proliferation of breast cancer cells by promoting G1/S phase transition." (PMID 36544490, 2022). "In addition, reports have suggested that TNNT1 could contribute to cell proliferation in breast cancer." (PMID 33050659, 2020).
congenital myopathy (6 papers, 2016 to 2025). "Using functional analyses we investigated the mechanism by which the variant causes disease, and clarify OCPMD as a model of TNNT1 congenital myopathy." (PMID 32819427, 2020). "Recently, two novel recessive variants in TNNT1 leading to congenital myopathy were described." (PMID 34502093, 2021). "Thus, recessive variants of TNNT1 can manifest into a congenital myopathy." (PMID 34502093, 2021). "This is likely to contribute to the marked muscle symptoms observed in TNNT1‐related congenital myopathies." (PMID 40320982, 2025). "Identification of the causative variant in TNNT1 finally clarifies that the OCPMD sheep is in fact a large animal model of TNNT1 congenital myopathy." (PMID 32819427, 2020). "As TNNT1 pathogenic variants have impacts on both slow and fast twitch muscle fibres, our findings emphasize that a combination of mavacamten and fast myosin inhibitor may be considered the preferential choices for TNNT1‐related congenital myopathies." (PMID 40320982, 2025). "TNNT1 is one of at least 12 genes reported to be implicated in NEM, a congenital myopathy." (PMID 34502093, 2021). "A single base deletion in the TNNT1 gene, which encodes slow skeletal troponin T, has been identified as the causative mutation in ovine congenital progressive muscular dystrophy (OCPMD), effectively reclassifying this disorder as a form of TNNT1-related congenital myopathy." (PMID 40933525, 2025).
endometrial cancer (5 papers, 2015 to 2025). Primary or metastatic malignant neoplasm involving the endometrium (mucous membrane that lines the endometrial cavity). "TNNT1 is a subunit of troponin that has been found to be upregulated in a variety of tumor tissues, including breast, colorectal and endometrial cancers." (PMID 36672336, 2023). "As for EC, TNNT1 was differentially expressed when mixed-type endometrial carcinomas were compared to pure low-grade endometrioid adenocarcinoma." (PMID 31557240, 2019). "A separate study examining gene expression changes in human endometrial carcinoma tissue revealed that TNNT1 is differentially expressed, depending on the specific subtype of endometrial carcinoma." (PMID 29416706, 2018). "However, the expression of these metastatic genes, S100A4 and TNNT1, was similar in both type I and type II endometrial cancer." (PMID 40433700, 2025). "We also checked for the expression of genes involved in facilitating metastasis in endometrial cancer, such as S100A4 and TNNT1." (PMID 40433700, 2025). "It is not clear how this gene could be involved in endometrial cancer etiology although TNNT1 is overexpressed in metastatic uterine leiomyosarcoma, which suggests TNNT1 is associated with more aggressive tumor cell phenotypes." (PMID 26132201, 2015).
cardiomyopathy (3 papers, 2014 to 2020). A disease of the heart muscle or myocardium proper. "In humans, a variety of cardiomyopathies are associated with mutations in all three cardiac troponin subunits (TNNT1, TNNT2, and TNNT3)." (PMID 33329019, 2020). "We assumed that miR-1246 might target UBE2C, TNNT1, TRAIP, and UCHL1 during the regulation of ubiquitin-mediated proteolysis, glycosaminoglycan binding, DNA metabolism, the PI3K–Akt–mTOR signaling pathway, the neurotrophin and cardiomyopathy signaling pathway, and the MAPK signaling pathway." (PMID 33050659, 2020).
nemaline myopathy 5 (3 papers, 2014 to 2024). "Variants in TNNT1 cause nemaline myopathy 5 in Human, which has a severe phenotype, leading to loss of slow twitch myofibers." (PMID 38704563, 2024). "The loss of Tnnt1 results in a recessive Amish nemaline myopathy with lethal respiratory failure." (PMID 24701242, 2014).
Obesity (3 papers, 2020 to 2025). Accumulation of substantial excess body fat. "Studies have found that TNNT1 is directly associated with obesity traits, and increased TNNT1 expression is positively correlated with triglycerides." (PMID 35480309, 2022).
colon cancer (2 papers, 2021). "Studies have reported that TNNT1 is significantly upregulated in colon cancer samples and cell lines." (PMID 34795697, 2021). "Similar results were found that elevated BST2 level, HOXC6, and TNNT1 level are correlated with poor prognosis in colon cancer patients, while TNNT1 protein may be mediated through the process of epithelial–mesenchymal transition." (PMID 34381786, 2021).
gallbladder carcinoma (2 papers, 2017 to 2019). "In the context of cancer, tumor progression of gallbladder carcinoma is positively associated with TNNT1 expression." (PMID 31557240, 2019).
heart failure (2 papers, 2016 to 2023). Inability of the heart to pump blood at an adequate rate to meet tissue metabolic requirements. "Tnnt1 codes for slow skeletal troponin T, and its expression has been shown to increase in end-stage human heart failure." (PMID 36889588, 2023).
hypertrophic cardiomyopathy (2 papers, 2015 to 2020). A condition in which the myocardium is hypertrophied without an obvious cause. "Serum TNNT1 levels had a positive association with increased risk for hypertrophic cardiomyopathy and also with different conditions related to the severity of the disease." (PMID 25970782, 2015).
pancreatic cancer (2 papers, 2018 to 2022). "This trend is most pronounced in pancreatic cancer patients with high TNNT1 expression, where survival probability drops precipitously within a 2-year time span." (PMID 29416706, 2018). "Patients with renal, endometrial, colorectal, and pancreatic cancer concomitant with high TNNT1 expression have an unfavorable prognosis compared to patients with low TNNT1 expression." (PMID 29416706, 2018). "Analysis of the expression level of the hub genes indicated that the genes TNNT1, KCNN4, SH2D3A, and PHLDA2 were differentially expressed between 179 pancreatic tumors and 171 normal tissue samples." (PMID 35712127, 2022). "The expression level of genes TNNT1, KCNN4, SH2D3A, and PHLDA2 was significantly different between the 179 pancreatic tumors and 171 normal tissue samples." (PMID 35712127, 2022).
breast tumor (1 paper, 2022). "A previous study reported that TNNT1 is significantly upregulated in breast tumor samples, and it facilitated their uncontrolled proliferation of tumor cells." (PMID 35712127, 2022).
diabetes mellitus (1 paper, 2020). A metabolic disorder characterized by abnormally high blood sugar levels due to diminished production of insulin or insulin resistance/desensitization. "The results of this research may help explain the induction of tacrolimus-induced posttransplantation diabetes mellitus via the low expression of muscle genes including Tpm3, Tnnc1, Tnnt1, Tnni3, Hrh3, Apln, S1pr3, and Cxcl12." (PMID 31998808, 2020).
diffuse midline glioma (1 paper, 2021). A diffuse glioma that arises from the midline structures of the central nervous system. "The overexpression of TNNT1 may play a role in the development of diffuse midline gliomas (DMGs)." (PMID 34026368, 2021).
Ewing sarcoma (1 paper, 2014). A small round cell tumor that lacks morphologic, immunohistochemical, and electron microscopic evidence of neuroectodermal differentiation. "Strong connection links on certain genes (TNNT1 and FNDC5 in rhabdomyosarcoma (RMS); FCGRT and OLFM1 in Ewing’s sarcoma (EWS)) suggested their potency as central hubs in the interconnection of genes with different functionalities." (PMID 25025207, 2014).
lung adenocarcinoma (1 paper, 2020). A carcinoma that arises from the lung and is characterized by the presence of malignant glandular epithelial cells. "The results explained that the high expression of UBE2C, UCHL1, TRAIP, TNNT1, TNNI3, and RAC3 were associated with poor overall survival of lung adenocarcinoma patients (p < 0.05)." (PMID 33050659, 2020).
rhabdomyolysis (1 paper, 2025). Necrosis or disintegration of skeletal muscle often followed by myoglobinuria. "TNNT1 (Troponin T1, Slow Skeletal Type) encodes a protein that regulates the contraction of slow twitch striated muscles and is released from injured muscle tissue, thus serving as a diagnostic marker of exercise-induced muscle injury and possible rhabdomyolysis." (PMID 40149400, 2025).
rotator cuff tears (1 paper, 2022). "Some co-expressed mRNAs of LINC01405 (TNNT1 and MYH7) have also been reported in a study of rotator cuff tears." (PMID 36111133, 2022).
skeletal myopathies (1 paper, 2023). "Mutations in the 3 TnT isoform genes (i.e., TNNT1, TNNT2, and TNNT3) have been found in cardiac and skeletal myopathies, suggesting that TnT plays a key role in striated muscle growth and function." (PMID 37186966, 2023).